CRP (C-reactive protein)
Diseases named in the same sentence as CRP in open-access papers (continued):
Sharing a sentence is not in itself a finding about the gene and the disease.
bacterial infection (continued). "However, CRP does not necessarily indicate bacterial infection, with the highest concentrations commonly seen in more severe cases." (PMID 35500008, 2022). "In addition, we tested whether conventional inflammation biomarkers (e.g., CRP, PCT, IL-6) could effectively identify and predict bacterial infections during the 28-day observation period in patients following liver transplantation." (PMID 35883545, 2022). "Additionally, the differences between median CRP levels were not significant between ACLF grade 1 or 2 patients with or without bacterial infections." (PMID 36143057, 2022). "PCT and CRP were higher than normal, which could not be distinguished from bacterial infections by clinical symptoms and laboratory tests." (PMID 35402461, 2022). "PCT (OR = 2.23, 95% CI: 1.55–3.19; p < 0.001), CRP (OR 1.62, 95% CI 1.08–2.44; p = 0.020), and qSOFA (OR 1.48, 95% CI 1.03–1.98; p < 0.001) were found to be the independent predictors of culture-proven bacterial infection, but presepsin was not." (PMID 36072944, 2022). "Indeed, none of these biomarkers (PCT, CRP) revealed significant differences between patients with or without a bacterial infection in our study." (PMID 35883545, 2022). "Nevertheless, our study showed that measured CRP concentration could not reliably identify bacterial infection." (PMID 35883545, 2022). "PCT is only sensitive to bacterial infection, while CRP is not sensitive to this pathogen." (PMID 35144683, 2022). "Moreover, low levels of serum CRP corroborate a lack of a general immune response to possible bacterial infection." (PMID 36555871, 2022). "Regarding to conventional biomarkers, Wyllie and colleagues have determined that CRP alone could not precisely predict bacterial infection than lymphocytopenia alone or a combination of lymphocytopenia and neutrophilia." (PMID 33622247, 2021). "Serial CRP with an in- or decrease over time may help to identify or rule out nosocomial bacterial infections and prompt appropriate use of antibiotic therapy." (PMID 34021897, 2021). "Our findings were compatible with earlier studies reporting that CRP may show a delayed increase during the course of bacterial infection, leading to false-negative tests in the early stages of the disease." (PMID 34115780, 2021). "We found the optimal CRP cut-off point was 22 mg/L, but that it alone could not identify whether it was a viral or bacterial infection in our patients." (PMID 34583675, 2021). "Considering that there is a risk of competition for patients who died in 30 days without bacterial infection, a competing-risk analysis was performed, and the correlation between 30-day CSI and baseline CRP level was consistent with the results of non-competitive models." (PMID 34439862, 2021). "Either CRP ≤ 22 mg/L or PCT ≤ 0.18 ng/mL combined with rhinorrhea could help distinguish viral from bacterial infections in hospitalized non-ICU adults with LRTI." (PMID 34583675, 2021). "The response time to bacterial infections is delayed (CRP, 6 h; PCT, 2–3 h), production triggers might not be living bacteria (CRP, cytokine; PCT, endotoxin and cytokine), and serum half-time is long (CRP, 4–6 h; PCT, 20–24 h)." (PMID 34641833, 2021). "Later on during ICU stay, serial PCT and, to a lesser extent, CRP may help to identify or rule out nosocomial bacterial infections and prompt appropriate use of antibiotic therapy." (PMID 33023606, 2020). "In our study, germiculture was not performed at baseline time, but antibiotics use (elevated serum WBC, CRP, and PCT levels), which might reflect bacterial infection to some aspect, was not an independent risk factor for disease progression." (PMID 33108255, 2020). "The lower serum CRP levels as well as synovial fluid counts in fungal PJIs may suggest that the inflammatory response is not as robust as one would expect to see in a bacterial infection." (PMID 32454521, 2020). "Most patients with other bacterial infections did not have elevated serum CRP level." (PMID 30685351, 2020).
bacterial infection (continued). "Our study clearly showed that also trauma or surgery without evidence of bacterial infection might induce an extreme increase in CRP concentrations > 100 mg/l." (PMID 32434519, 2020). "Based on CRP, a detection of bacterial infection was not possible." (PMID 32434519, 2020). "Although laboratory findings such as neutrophil, lymphocyte and white blood cell (WBC) counts and an elevated C-reactive protein (CRP) level may be suggestive of a bacterial infection, they are not sufficient for the identification of the pathogenic agent." (PMID 31428594, 2019). "Elevated CRP levels in children with HAdV infection in the absence of secondary bacterial infection indicated that HAdV triggered an inflammatory host response similar to that of a bacterial infection." (PMID 31370781, 2019). "The reference value of PCT and CRP applied to predicting bacterial infection in most clinical cases may not be suitable for GPP patients." (PMID 31777354, 2019). "However, the usefulness of biological markers, particularly CRP and PCT, has been investigated in order to differentiate between AECOPD and CAP, and to identify bacterial infections that could benefit from antibiotic treatment." (PMID 29904014, 2018). "C-reactive protein is also not specific for bacterial infection." (PMID 29234596, 2018). "Besides, we do not have information about some confounding factors of CRP level, such as bacterial infection, autoimmune, and so forth." (PMID 28801571, 2017). "Alongside these efforts to identify new combinations of biomarkers, research groups in Southeast Asia have been exploring the use of C-reactive protein (CRP) to differentiate bacterial infections from non-bacterial infections in Southeast Asia, albeit with limited specificity." (PMID 28753985, 2017). "The use of the CRP test has demonstrated to be effective without additional interventions for decreasing prescription of antibiotics as it helps the GP to rule out a bacterial infection and helps the GP to establish a dialogue with the patient about the need for antibiotics." (PMID 29240687, 2017). "Moreover, CRP levels reach peak values between 48 and 72 h after the onset of bacterial infection, and CRP does not precisely indicate the severity of bacterial infections at a single time point." (PMID 27778190, 2016). "But the specificity of the serum CRP level in the diagnosis of bacterial infection was not ideal." (PMID 28083019, 2016). "However, as the guideline did not include a dominating conception among GPs using the strategy “Clinical picture and CRP”, namely unspecified bacterial infection, it was not perceived relevant for their clinical practice." (PMID 27188438, 2016). "The moderate positive likelihood ratio of 1.9 for the lower CRP threshold therefore implies limited additional benefit in confirming the presence of bacterial infections, but the negative likelihood ratio of 0.1 implies high confidence in ruling out the need for antibiotics." (PMID 26558692, 2015). "In the present case, these diagnoses could be excluded clinically, due to the normal microbial flora of skin, and by a negative C-reactive protein, which is highly sensitive to bacterial infection." (PMID 24884686, 2014). "Even though CRP has a limited value for the differential diagnosis of bacterial infections due to the non-specific elevation in patients with inflammation from other causes, profound elevation of CRP early after HSCT was in general caused by infectious diseases." (PMID 24795865, 2014). "Rather, the results suggest that CRP acting non-specifically, may contribute to the bacterial infection clearance." (PMID 23941472, 2013). "PCT was not a better marker of bacterial infection than CRP in the study by Chan and colleagues." (PMID 16569262, 2006).
bacterial infection (continued). "Of the cases in which the CRP band was positive, 46·6% (62/133), 17·3% (23/133), 15·8% (21/133), 15·8% (21/133) and 4·51% (6/133) were classified as non-bacterial infection, probable non-bacterial infection, bacterial infection, indeterminate, and probable bacterial infection, respectively." (PMID 39177882, 2025). "However, more recent studies suggest that PCT may not be superior to CRP for monitoring of treatment response in humans with bacterial infections." (PMID 40607352, 2025). "PCT markers have considerably higher accuracy than do CRP markers for discerning bacterial infections from non-infectious causes of inflammation, in a meta-analysis, the pooled sensitivity for PCT markers was 88% (95% CI, 80–93%), compared with 75% (95% CI, 62–84%) for CRP marker." (PMID 40806926, 2025). "It has been shown that C-reactive protein levels may not rise in the case of bacterial infection in patients treated with tocilizumab, and, given the rising number of molecular-targeted immunosuppressive drugs, it is possible that other drugs may have the same effect." (PMID 36673130, 2023). "However, application of PCT as an add-on when an ARTI is not trivial (e.g. CRP values are above 20 mg/L), may aid the GP in ruling out a serious bacterial infection." (PMID 35279069, 2022). "Additionally, we determined the serum levels of CRP and IL-6, as standard inflammation markers for assessing the systemic inflammatory response of the patients, and of PCT, as a parameter that helps to discriminate between bacterial and non-bacterial infections." (PMID 33903660, 2021). "In addition to clinical findings, some studies have suggested that laboratory findings, such as white blood cell count (WBC), absolute neutrophil count (ANC), C-reactive protein (CRP), and procalcitonin (PCT), may be useful in helping physicians recognize children with severe bacterial infection." (PMID 32429293, 2020). "The use of CRP-guided antibiotic therapy, without the surveillance data, would avert an additional 325 deaths due to identification of a greater proportion of patients with bacterial infections whom may benefit from antibiotic treatment." (PMID 31245630, 2019). "Whereas no clinical ranges have been so far reported for FAK, for CRP it is well known that its concentration in human serum in healthy patients is usually lower than 10 μg/mL and it can increase to higher levels in case of inflammation, and viral or bacterial infections (10–200 μg/mL)." (PMID 24481229, 2014). "Inflammatory markers such as serum amyloid A (SAA), C-reactive protein (CRP), and white blood cell (WBC) counts in RV diarrhea are significantly lower than in bacterial infections; thus, RV diarrhea is considered non-inflammatory." (PMID 40430800, 2025). "C-reactive protein (CRP) is a frequently used marker of inflammation in dogs, but is not specific for bacterial infection." (PMID 40607352, 2025). "Routine biochemical markers such as white blood cell count (WBC) and C-reactive protein (CRP) can be elevated in various inflammatory conditions and do not specifically indicate bacterial infection." (PMID 41262450, 2025). "Raised CRP and ESR in the absence of a clear source should be alarm signs that prompt consideration of occult bacterial infection, including IE, which can follow a prolonged subacute course, typically without fever." (PMID 41246729, 2025). "There was a statistically significant difference in CRP (p = 0.014), PCT (p < 0.0001), IL-6 (p = 0.007), and WBC (p = 0.024), but not in temperature (p = 0.216), between the CAP-only and No Bacterial Infection groups." (PMID 38391578, 2024). "Inflammatory markers such as C-reactive protein (CRP) and erythrocyte sedimentation rate (ESR) are typically elevated in bacterial infections, but can be nonspecific." (PMID 39699542, 2024).
bacterial infection (continued). "As clinical findings and C-Reactive Protein (CRP) have not been highly accurate in differentiating viral and bacterial infections in children, companies have attempted to develop new diagnostics." (PMID 38539385, 2024). "In comparison to patients without bacterial infection, patients with bacterial co-infection had a significantly higher serum PCT, CRP, and lactic dehydrogenase (LDH) level at admission (p < 0.05)." (PMID 38246947, 2024). "Accumulating evidence has shown that levels of inflammatory biomarkers, including WBC, CRP, NE%, ESR, PCT, IL-6, and IL-10, were significantly higher in patients with bacterial infection than those with non-bacterial infection." (PMID 37986183, 2023). "The result showed that the positive rate of CRP was significantly higher in IP patients than in non-IP patients, instead of PCT which was related to bacterial infection." (PMID 36600276, 2023). "We plotted ROC curves for nCD64, CRP and WBC, comparing patients with bacterial infections to a control group consisting of the viral and non-infectious groups." (PMID 36915043, 2023). "WBC, CRP and IL-6 have a lack of specificity, and PCT is mainly used to determine if a bacterial infection is present and to guide the use of antibiotics." (PMID 37158819, 2023). "Nonetheless, similar to CRP, elevated PCT is not 100% specific for bacterial infections and can be seen in other systemic inflammatory responses." (PMID 35500008, 2022). "The combination of substantially elevated CRP and relatively low PCT levels tested between 12 and 24 h after fever onset strongly suggest that immunocompromised children have IFI rather than bacterial infection." (PMID 35740137, 2022). "In our cases, the mean serum CRP and ESR were generally not high (33.5 ± 31.7 mg/L and 70.9 ± 30.9 mm/h, respectively), compared to bacterial infections." (PMID 36506031, 2022). "Moreover, since inflammatory markers, such as CRP and leukocyte count, are not specific for any particular bacterial infection, it would be interesting to study whether indicators of systemic inflammation, such as laboratory markers, can be decreased more efficiently." (PMID 36556274, 2022). "PCT, CRP and WBC can be combined as effective indicators for the identification of acute bacterial or no-bacterial infections in children." (PMID 34836530, 2021). "Several prior studies have assessed the utility of non-specific inflammatory biomarkers such as C-reactive protein (CRP), white cell count (WBC) and absolute neutrophil count (ANC) to discriminate probable bacterial infections from non-bacterial infections." (PMID 34244563, 2021). "There has been a renewed interest in PCT during the COVID-19 pandemic, where patients are presenting with raised systemic inflammatory markers (e.g., CRP and white cell count (WCC)) independent of bacterial infection." (PMID 34572701, 2021). "In comparison, AUROCs for bacterial vs. viral/noninfected patients for other biomarkers used to diagnose bacterial infections were as follows: PCT (0.88, 95%CI 0.79–0.96), CRP (0.80, 95% CI 0.72–89), and white blood cell counts (0.78, 95% CI 0.69–0.87)." (PMID 34142256, 2021). "Irrespective of age, both CRP and PCT concentrations rise in response to both bacterial infection and non-infectious inflammation." (PMID 34079538, 2021). "The NLR, LMR, PLR, monocyte count, AAR, C-reactive protein (CRP), CTP, and MELD values were significantly different in the group of patients with bacterial infection, compared to those of noninfected patients." (PMID 32155772, 2020). "We compared performance of IMX-BVN-1 to that of PCT and CRP only for microbiology-positive patients, since PCT was used by the adjudicators in determining bacterial infection status in microbiology-negative cases." (PMID 32132525, 2020).
bacterial infection (continued). "The accuracy of PCT measured on day 0 of fever was significantly higher, with an AUC value of 0.715, than that of other inflammatory markers such as CRP and WBC counts to discriminate a fever related to bacterial infection from a noninfectious fever." (PMID 29849829, 2018). "Elevated ferritin and sIL2R seem to be good markers, while inflammatory markers like CRP and PCT are not useful to discriminate viral triggered HLH from severe bacterial infection." (PMID 29411124, 2018). "Elevated ferritin seems to be a good marker, while inflammatory markers like CRP and PCT are not useful to discriminate viral triggered HLH from severe bacterial infection." (PMID 29411124, 2018). "As a single indicator of bacterial infection, both WBC and CRP did not provide sufficient accuracy to justify their use in assessing children with non‐severe febrile illness." (PMID 27935664, 2017). "The positive rates of the PCT, CRP and WBC levels of the bacterial infection group were higher than those of the non-bacterial infection group, and the differences were statistically significant (P<0.05), as shown in Table-II." (PMID 28083019, 2016). "While many of the identified host biomarkers are currently available in commercial assays (i.e. blood cell counts, ESR, CRP, PCT, calprotectin), most existing assays are not specifically designed to differentiate bacterial from non-bacterial infections." (PMID 27486746, 2016). "In HIV-uninfected children, CRP and PCT were also higher in children with SBI compared to those with no detectable bacterial infection (p<0.0005), and CD163 was higher in non-survivors (p = 0.05)." (PMID 19675669, 2009). "C-reactive protein (CRP) is a real-time and low-cost biomarker to distinguish febrile bacterial infections from non-bacterial febrile illnesses." (PMID 19351421, 2009). "The median CRP, CRPv and PCT were significantly higher for the patients with bacterial infections than for the patients with non-bacterial febrile illness." (PMID 19351421, 2009). "In HIV-infected children, CRP and PCT were higher in children with SBI compared to those with no detectable bacterial infection (p<0.0005), and PCT and CD163 were higher in non-survivors (p = 0.001, p = 0.05 respectively)." (PMID 19675669, 2009). "Lastly, clinical studies using urine samples from febrile patients revealed significantly elevated levels of m2A during bacterial infections, and these values did not correlate with inflammation severity markers, such as white blood count (WBC) and C-reactive protein (CRP)." (PMID 39660929, 2025). "During the first week, PCT, CRP, and WBC levels may vary due to the recovery process and are not reliable indicators of bacterial infections." (PMID 41007066, 2025). "On the other hand, changing conditions reduce the concern about sample duplication as well as bias related to patient-specific patterns and prevent sole sampling at the highest CRP/PCT values (which, as exemplified above, do not necessarily reflect the status of bacterial infection)." (PMID 39766187, 2024). "However, when compared with other inflammatory markers such as C‐reactive protein (CRP), PCT was not better as a marker of bacterial infection in emergency patients." (PMID 39305165, 2024). "Many agreed that CRP POC testing could help to evaluate disease severity in patients who are known COVID-positive, potentially ruling out a superimposed bacterial infection or indicating the need for hospitalization regardless of the underlying etiology." (PMID 36673130, 2023). "Patients with and without secondary bacterial infection in relation to PCT and CRP were compared." (PMID 34021897, 2021). "At pre-test probabilities 0.35 and 0.72, the combined SeptiCyteTM score achieved a negative predictive value for bacterial infection of 0.97 (0.90–0.99) and 0.86 (0.64–0.96), compared to 0.90 (0.80–0.94) and 0.66 (0.48–0.79) for WCC and 0.88 (0.69–0.95) and 0.60 (0.31–0.72) for CRP." (PMID 32690014, 2020).